CASC2 (cancer susceptibility 2)
Diseases named in the same sentence as CASC2 in open-access papers (continued):
Sharing a sentence is not in itself a finding about the gene and the disease.
colorectal cancer (17 papers, 2015 to 2024). A primary or metastatic malignant neoplasm that affects the colon or rectum. "In 76% CRC (colorectal cancer) patients (n = 68) CASC2 low expression was associated with tumor stage." (PMID 33120918, 2020). "For the 5 identified lncRNA markers, CASC2 has been reported to be associated with colorectal cancer." (PMID 31470869, 2019). "LncRNA CASC2 (cancer susceptibility candidate 2) was originally described as a tumor suppressor gene in endometrial and colorectal cancers." (PMID 27686732, 2016). "CASC2 (Cancer susceptibility 2) is a tumor suppressor gene that has been associated with several types of cancers, including endometrial, lung, gastric, and colorectal cancers; however, there is limited research on its possible involvement in HS." (PMID 38792557, 2024). "Besides, berberine was also illustrated to promoted apoptosis of colorectal cancer via regulation of the long noncoding RNA (lncRNA) cancer susceptibility candidate 2 (CASC2)/AU-Binding Factor 1 (AUF1)/B-Cell CLL/Lymphoma 2 (Bcl-2) Axis." (PMID 32328135, 2020). "Similarly, in colorectal cancer the loss of lncRNA Casc2 (Cancer susceptibility candidate 2), which normally functions to suppress errant STAT3 signaling by directing PIAS3 expression, has been associated with disease progression." (PMID 31842362, 2019). "Elevation of CASC2 expression can impair the proliferation of colorectal cancer (CRC) cells and suppress tumor growth in vivo." (PMID 38267746, 2024). "There are many antitumor mechanisms induced by BBR in human colorectal cancer cells, such as suppression of cell viability, induction of cell apoptosis, and upregulation of CASC2 lncRNA." (PMID 34885950, 2021). "Recently, it was demonstrated that CASC2 in colorectal cancer is functioning as ceRNA for miR-18a, thereby modulating the expression of target gene PIAS3, and subsequently inhibiting CRC cell proliferation and tumor growth." (PMID 33120918, 2020). "Studies have revealed that the deregulation of CASC2 by miRNA hsa-mir-21 and hsa-mir-18a increases the proliferation and migration of cancer cells in colorectal cancer." (PMID 31470869, 2019). "Further experiments were conducted to investigate the biological function of CASC2 with respect to colorectal cancer cell phenotypes in vitro and in vivo." (PMID 27198161, 2016). "Evidence indicates that other members of the CASC family (CASC2, CASC11, CASC9) could be associated with enhanced or reduced proliferation, invasion, and apoptosis in cervical and colorectal cancers." (PMID 35887085, 2022). "Besides, the long noncoding RNA CASC2 functions as a competing endogenous RNA by sponging miR-18a in colorectal cancer." (PMID 28199978, 2017). "For instance, CASC2 is able to repress the expression of miR-18a-5p, thereby inducing PIAS3 (Protein Inhibitor of Activated STAT 3) expression in colorectal cancer cells." (PMID 32549759, 2020). "Additionally, mechanistic analysis reveals that CASC2 might function as a ceRNA to regulate PIAS3 expression by sponging miR-18a, thus playing a critical role in the pathobiology of human colorectal cancer." (PMID 27198161, 2016).
hepatocellular carcinoma (15 papers, 2017 to 2024). A malignant tumor that arises from hepatocytes. "Higher CASC2 expression causes slight up-regulation in the survival of patients with hepatocellular carcinoma; lower miR-24 and miR-221 expression is significantly correlated with longer survival of patients with hepatocellular carcinoma." (PMID 29476051, 2018). "For instance, we found that lncRNA CASC2 suppresses epithelial-mesenchymal transition of hepatocellular carcinoma cells through the CASC2/miR-367/ F-box and WD repeat domain containing 7 (FBXW7) axis." (PMID 33596983, 2021). "TCGA hepatocellular carcinoma data (TCGA_LIHC) were analyzed using Spearman’s correlation analysis, and it has been found that lncRNA CASC2 was weakly negatively correlated with RELA." (PMID 35145900, 2021). "LncRNA CASC2 hinders epithelial–mesenchymal transition in hepatocellular carcinoma cells through miR-367/FBXW7 axis." (PMID 31868202, 2020). "Studies in hepatocellular carcinoma revealed that CASC2 prohibited mesenchymal–epithelial transition progression and exerted anti-metastatic effect via CASC2/mirR-396/FBXW7 axis." (PMID 33120918, 2020). "LncRNA CASC2 has been reported to possess antitumor effect in many cancers, including hepatocellular carcinoma, gastric cancer, and cervical cancer." (PMID 31134151, 2019). "CASC2 has been reported to inhibit cancer cell proliferation, including hepatocellular carcinoma cell proliferation." (PMID 29476051, 2018). "Consistent with its function in other cancers, CASC2 knockdown significantly promoted tumor cell viability, suppressed tumor cell apoptosis, and increased the resistance of hepatocellular carcinoma cell to TRAIL." (PMID 29476051, 2018). "In hepatocellular carcinoma, the well-established tumor suppressive lncRNA of CASC2 could serve as a sponge of miR-24 and miR-221, and thus modulate TRAIL-induced tumor cell apoptosis." (PMID 34282054, 2021). "In addition, it has been reported that lncRNA CASC2 inhibited metastasis and epithelial to mesenchymal transition of hepatocellular carcinoma and lung adenocarcinoma cells." (PMID 30857524, 2019). "Herein, we evaluated the role of CASC2 in TRAIL resistance of hepatocellular carcinoma." (PMID 29476051, 2018). "LncRNA CASC2 overexpression suppressed cell proliferation and tumor growth in mice in hepatocellular carcinoma (HCC)." (PMID 35928868, 2022). "A previous study reported that the expression of CASC2 was reduced in the hepatocellular carcinoma (HCC) tissues compared with the normal tissues." (PMID 31134151, 2019). "However, the role of lncRNA CASC2 in hepatocellular carcinoma (HCC) remains mostly unknown." (PMID 36816357, 2023). "However, the expression and function of CASC2 in hepatocellular carcinoma (HCC) remain unclear." (PMID 28716020, 2017). "In addition, we revealed that CASC2, a well-established tumor suppressive long non-coding RNA, could serve as a “Sponge” of miR-24 and miR-221, thus modulating TRAIL-induced tumor cell apoptosis TRAIL resistance of hepatocellular carcinoma." (PMID 29476051, 2018).
cervical cancer (12 papers, 2018 to 2023). A primary or metastatic malignant neoplasm involving the cervix. "In addition, cancer susceptibility candidate 2 (CASC2) is an lncRNAs with low expression in cervical cancer." (PMID 36890809, 2023). "Furthermore, an overexpression of lncRNA cancer susceptibility candidate 2 (CASC2) in cervical cancer inhibits angiogenesis in vitro via the MAPK pathway." (PMID 32992718, 2020). "Upregulation of CASC2 increased the cisplatin sensitivity in cisplatin-resistant cervical cancer cells by suppression of miR-21 and upregulation of PTEN and inactivation of pAkt." (PMID 36438563, 2022). "The expression of lncRNA CASC2 was decreased in cervical cancer samples, which was related with poor prognosis and a shorter OS." (PMID 36438563, 2022). "Exogenous CASC2 amplified the repression of proliferation of cervical cancer cells induced by cisplatin treatment." (PMID 36438563, 2022). "It has been demonstrated that CASC2 was low-expressed in the cisplatin-resistant cervical cancer tissues compared to cisplatin-sensitive cancer tissues and overexpression of CACS2 sensitized cisplatin-resistant cervical cancer cells to cisplatin." (PMID 31134151, 2019). "In cisplatin-resistant cervical cancer cells, CASC2 upregulates PTEN expression by directly inhibiting miR-21 and inactivation of AKT signaling." (PMID 31728180, 2019). "A previous study showed that the expression of CASC2 was down-regulated in cervical cancer tissues and CASC2 expression was related to a shorter survival time and poorer clinicopathologic features." (PMID 35542225, 2018). "This suggests that low CASC2 expression contributes to cisplatin resistance in cervical cancer." (PMID 36890809, 2023). "Cisplatin-resistant cervical cancer patients had lower expression of lncRNA CASC2." (PMID 36438563, 2022). "In the course of our research, reports demonstrated that lncRNA CASC2 sponges miR-21 in oral squamous cell carcinoma and in the modulation of sensitizes cervical cancer to cisplatin, and lncRNA FTX can also negatively control miR-21-5p during status epilepticus." (PMID 33203802, 2020). "LncRNA CASC2 acts as a sponge for miR-21 to sensitize cervical cancer to cisplatin." (PMID 30992025, 2019). "Suppression of CASC2 expression can significantly attenuate cisplatin's inhibition of cervical cancer cell proliferation and increase the median lethal dose (IC50), while overexpression can enhance cisplatin's inhibition of cervical cancer cell proliferation and decrease the IC50 value." (PMID 36890809, 2023). "Mechanistic studies have shown that CASC2 can competitively inhibit miR-21, thereby increasing the miR-21 expression of the downstream target protein PTEN (tumor suppressor), and PTEN can increase the chemosensitivity of cervical cancer cells to cisplatin by regulating the AKT signaling pathway." (PMID 36890809, 2023). "In addition, CASC2 can competitively bind to miR-21 and upregulate the expression of PTEN, the downstream target protein of miR-21, thereby promoting the chemosensitivity of cervical cancer cells to cisplatin and inhibiting the development of cervical cancer." (PMID 36890809, 2023).
osteosarcoma (9 papers, 2017 to 2023). A usually aggressive malignant bone-forming mesenchymal neoplasm, predominantly affecting adolescents and young adults. "Other than MALAT-1 and PANDA, lncRNA Cancer susceptibility candidate 2 (CASC2) is significantly downregulated both in human osteosarcoma tissue and osteosarcoma cell lines MG-63, U2OS, SAOS2, and SOSP-9607 (p < 0.01)." (PMID 29657304, 2018). "In osteosarcoma, CASC2 expression downregulation was observed in patient tissue samples and cell lines, and low expression in tissue was associated with poor tumor differentiation, higher malignancy grade, and shortened patient survival." (PMID 33120918, 2020). "At the same way, experimental overexpression of CASC2 results in reduced infiltration, colony formation, and cellular growth in osteosarcoma cell-lines." (PMID 29657304, 2018). "CASC2 also inhibits osteosarcoma progression in a subcutaneous mouse xenograft model." (PMID 37469450, 2023). "In osteosarcoma, the most frequent primary bone tumor, CASC2 levels are reduced compared with noncancerous cells, and its expression negatively correlates with more advanced stages of this tumor type." (PMID 37469450, 2023).
pancreatic cancer (9 papers, 2017 to 2025). "Cancer susceptibility candidate 2 (CASC2) exerted tumor-suppressive effects through regulation of miR-24/MUC6 axis in pancreatic cancer cells." (PMID 34178644, 2021). "In pancreatic cancer cells, ginsenoside Rg3 upregulates the expression levels of long noncoding RNA cancer susceptibility candidate 2 (CASC2) and PTEN, leading to the suppression and programmed cell death of pancreatic cancer cells that are resistant to gemcitabine." (PMID 40490812, 2025). "miR-24 knockdown or CASC2 overexpression suppressed pancreatic cancer cell proliferation, migration, invasion and promoted apoptosis." (PMID 34178644, 2021). "In vitro and in vivo studies in gemcitabine-resistant pancreatic cancer cells have shown that Rg3 can activate PTEN signaling by upregulation of CASC2, thereby reducing cell proliferation and tumor growth." (PMID 33805687, 2021). "This study aimed to explore the mechanism of CASC2 in the regulation of pancreatic cancer metastasis." (PMID 30675129, 2019). "In this study, we compared the levels of CASC2 in the pancreatic cancer cell lines CAPAN-1, BxPC-3, JF305, PANC-1 and SW1990 and in normal pancreatic HPDE6-C7 cells and analyzed the mechanism of the CASC2-regulated metastasis of PANC-1 cells." (PMID 30675129, 2019). "The overexpression of CASC2 inhibited the migration and invasion of pancreatic cancer cells, further supporting the idea that CASC2 acts as a tumor suppressor." (PMID 30675129, 2019). "The expression levels of CASC2 in human pancreatic cancer cell lines CAPAN-1, BxPC-3, JF305, PANC-1 and SW1990 and in normal human pancreatic HPDE6-C7 cells were assayed." (PMID 30675129, 2019). "CASC2 functions as a tumor suppressor in pancreatic cancer cells to inhibit tumor cell migration and invasion." (PMID 30675129, 2019). "We found that the overexpression of CASC2 significantly downregulated the expression of miR-21, suggesting that CASC2 inhibited pancreatic cancer cells via downregulation of miR-21." (PMID 30675129, 2019). "The knockdown of PTEN significantly abolishes the suppression of the invasion induced by CASC2 in pancreatic cancer cells (P < 0.001)." (PMID 30675129, 2019). "In this study, we showed that CASC2 was downregulated in the pancreatic cancer cell lines CAPAN-1, BxPC-3, JF305, and PANC-1 compared with levels in normal pancreatic HPDE6-C7 cells." (PMID 30675129, 2019). "The knockdown of PTEN significantly abolishes the suppression of the migration induced by CASC2 in pancreatic cancer cells (P < 0.001)." (PMID 30675129, 2019). "CASC2 expression was downregulated in the pancreatic cancer cell lines CAPAN-1, BxPC-3, JF305, PANC-1 and SW1990 compared with levels in normal human pancreatic HPDE6-C7 cells." (PMID 30675129, 2019). "The qRT-PCR analysis results showed that the levels of CASC2 in the pancreatic cancer cell lines were significantly lower than that in the normal human pancreatic cells (P < 0.01)." (PMID 30675129, 2019). "In conclusion, we demonstrated that CASC2 suppressed the migration and invasion of pancreatic cancer cells via the downregulation of miR-21." (PMID 30675129, 2019). "Previous studies have found that low expression of CASC2 and high level of miR-367 expression correlated with poor prognosis of lung cancer and pancreatic cancer." (PMID 28716020, 2017). "CASC2 is downregulated in many human carcinomas, including pancreatic cancer." (PMID 33805687, 2021). "Thus, CASC2 influenced the migration and invasion of pancreatic cancer cells through the post-transcriptional regulation of ceRNA, which suggests it can participate in the onset and development of tumors." (PMID 30675129, 2019). "However, the role of CASC2/miR-21/PTEN should be investigated in primary pancreatic cancer cells and in pancreatic cancer tissue in future studies." (PMID 30675129, 2019). "Levels of CASC2 expression are lower in pancreatic cancer tissue and cell lines." (PMID 30675129, 2019).
pancreatic cancer (continued). "Our work revealed a novel regulatory mechanism of the CASC2/miR-21/PTEN axis that may be important in pancreatic cancer." (PMID 30675129, 2019). "Thus, PTEN is downstream of miR-21/CASC2 in pancreatic cancer cells." (PMID 30675129, 2019). "However, the mechanisms of the effects of CASC2 in pancreatic cancer are unclear." (PMID 30675129, 2019). "Finally, our work revealed a novel regulatory mechanism of the CASC2/miR-21/PTEN axis that may be important in pancreatic cancer." (PMID 30675129, 2019). "Mechanistically, CASC2 sponged miR-24 and relieved the repressive effects of miR-24 on MUC6 to suppress pancreatic cancer growth and progression." (PMID 34178644, 2021). "Essentially, levels of CASC2 and PTEN were found to be considerably elevated in ginsenoside-treated pancreatic cancer cells." (PMID 34178644, 2021). "In pancreatic cancer, it was demonstrated that the PTEN/Akt signaling pathway is involved in CASC2 regulation by hepatocyte nuclear factor 1 alpha, a transcription factor." (PMID 30675129, 2019). "The knockdown of PTEN significantly abolished the antimetastatic effect of CASC2 in PANC-1 cells, further suggesting that CASC2 suppressed the metastasis of pancreatic cancer cells through the downregulation of miR-21 and the upregulation of PTEN." (PMID 30675129, 2019).
endometrial cancer (7 papers, 2014 to 2023). Primary or metastatic malignant neoplasm involving the endometrium (mucous membrane that lines the endometrial cavity). "Another lncRNA, Cancer Susceptibility Candidate 2 (CASC2), has been identified as a tumor suppressor in endometrial carcinoma and is known to control cell growth, migration, invasion, and cell death in several types of human cancers." (PMID 37706018, 2023). "lncRNA Cancer Susceptibility Candidate 2 (CASC2) was originally discovered in the endometrial cancer (EC) study and is located on human chromosome 10q26." (PMID 35845734, 2022). "Cancer susceptibility candidate 2 (CASC2) is a long non‐coding RNA, which is located on human chromosome 10; the dysregulation of CASC2 is firstly detected in patients with endometrial cancer." (PMID 35665444, 2022). "LncRNA Cancer Susceptibility Candidate 2 (CASC2), a novel human lncRNA mapping to 10q26 in humans, has been originally characterized as a downregulated gene and acted as a tumor suppressor gene in endometrial cancer." (PMID 28199978, 2017). "LncRNA Cancer Susceptibility Candidate 2 (CASC2) was first found in endometrial cancer in 2004 and could inhibit endometrial cancer carcinogenesis, which serves as a tumor suppressor." (PMID 36816357, 2023).
non-small cell lung carcinoma (7 papers, 2017 to 2022). A group of at least three distinct histological types of lung cancer, including non-small cell squamous cell carcinoma, adenocarcinoma, and large cell carcinoma. "In NSCLC (non-small-cell lung carcinoma) patients (n = 76), CASC2 expression was downregulated proportionally to the pathological stage and associated with tumor size, and this gene was an independent predictor for overall survival." (PMID 33120918, 2020). "Upregulation of CASC2 decreased the cell proliferation of non-small cell lung cancer, representing that CASC2 can be a potential prognostic marker and therapeutic target in non-small cell lung cancer therapy." (PMID 32760219, 2020). "In addition, low expression of long noncoding RNA CASC2 indicates a poor prognosis and regulates cell proliferation in non-small cell lung cancer and renal cell carcinoma cells." (PMID 28199978, 2017). "CASC2 negatively regulated miR-18a and miR-21, thus modulating PTEN/phosphoinositide 3-kinase (PI3K)/Akt pathway and cisplatin-induced viability inhibition in non-small cell lung cancer." (PMID 31134151, 2019).
diabetic nephropathy (6 papers, 2020 to 2025). "Studies in diabetic nephropathy models have identified SOCS2 as a target gene of miR‐144, which in turn can be targeted by cancer susceptibility candidate 2 (CASC2)." (PMID 40067024, 2025). "In diabetic nephropathy, CASC2 reduces HG-induced podocyte injury by mediating the miR-9-5p/PPARγ axis." (PMID 38405620, 2024). "CASC2 acts as a tumor suppressor in various types of cancers and its expression level is reduced in the serum of diabetic nephropathy patients, tissues in db/db diabetic mouse, and high glucose-treated human renal mesangial cells and podocyte cells." (PMID 35207562, 2022). "Upregulation of CASC2 has been shown to attenuate the progression of diabetic nephropathy via various pathways." (PMID 35207562, 2022). "Reduced CASC2 expression was observed in both in vivo and in vitro models of diabetic nephropathy." (PMID 40067024, 2025). "CASC2/miR-9-5p/PPARγ alleviates the high glucose-induced cell injury in diabetes nephropathy." (PMID 35935642, 2022). "Zhang’s study concluded that CASC2 upregulation suppressed high glucose-induced proliferation, oxidative stress of human mesangial cells and extracellular matrix accumulation through miR-133b/FOXP1 regulatory pathway, suggesting that CASC2 was a novel biomarker for diabetic nephropathy treatment." (PMID 35725478, 2022). "Overexpression of CASC2 mitigated cell apoptosis and the release of inflammatory factors such as IL‐1β, IL‐6, and TNF‐α through the miR‐144/SOCS2 axis, slowing the progression of diabetic nephropathy." (PMID 40067024, 2025).